SLC16A8 (solute carrier family 16 member 8)
Description:
Probable retinal pigment epithelium (RPE)-specific proton-coupled L-lactate transporter (By similarity). May facilitate transport of lactate and H(+) out of the retina and could therefore play a role in pH and ion homeostasis of the outer retina (By similarity).
Synonyms: MCT3; REMP
Tractability: Antibody: UniProt places it where antibodies can reach, with high confidence; its Gene Ontology location is reachable by antibodies, with high confidence; UniProt predicts a signal peptide or a membrane-spanning region.
Target class: SLC16 family of monocarboxylate transporters; Electrochemical transporter; SLC superfamily of solute carriers; Transporter
Gene: Protein-coding gene on chromosome 22 (38,078,134 to 38,084,184, reverse strand). Ensembl gene ENSG00000100156.
Subcellular location: Basolateral cell membrane
Subcellular location (Human Protein Atlas): Focal adhesion sites; Intermediate filaments
Pathways (Reactome):
Hemostasis: Basigin interactions
Transport of small molecules: Proton-coupled monocarboxylate transport
Gene Ontology:
Molecular function: lactate transmembrane transporter activity; monocarboxylic acid transmembrane transporter activity; transmembrane transporter activity
Biological process: lactate transport; lactate transmembrane transport; monocarboxylic acid transport; transmembrane transport
Cellular component: apical plasma membrane; basolateral plasma membrane; membrane; plasma membrane
Genetic constraint (gnomAD): Loss-of-function variants: 20 observed, 12.44 expected, observed/expected ratio (o/e) 1.61, 90% interval 1.1 to 1.94. The synonymous counts are far from expectation, so gnomAD's model fits this gene poorly and the ratio says little. Missense variants: 689 observed, 428.23 expected, observed/expected ratio (o/e) 1.61, 90% interval 1.51 to 1.71. Synonymous variants: 328 observed, 195.65 expected, observed/expected ratio (o/e) 1.68, 90% interval 1.53 to 1.84.
Homologues: Orthologues: chimpanzee SLC16A8 (99% identical), macaque SLC16A8 (97% identical), pig SLC16A8 (89% identical), dog SLC16A8 (88% identical), rat Slc16a8 (83% identical), mouse Slc16a8 (83% identical), guinea pig SLC16A8 (67% identical), zebrafish slc16a8 (55% identical), Drosophila melanogaster CG13907 (28% identical), Drosophila melanogaster Mct1 (27% identical), Drosophila melanogaster CG8468 (27% identical), Drosophila melanogaster Sln (26% identical), and 9 more. Paralogues in human: SLC16A3 (54% identical), SLC16A7 (40% identical), SLC16A1 (37% identical), SLC16A5 (35% identical), SLC16A12 (31% identical), SLC16A11 (31% identical), SLC16A13 (30% identical), SLC16A9 (26% identical), SLC16A6 (25% identical), SLC16A10 (24% identical), SLC16A14 (23% identical), SLC16A2 (22% identical), and 1 more.
Diseases named in the same sentence as SLC16A8 in open-access papers:
SLC16A8 is named in the same sentence as 8 diseases in open-access papers, as found by Europe PMC text mining. Sharing a sentence is not in itself a finding about the gene and the disease. The quoted sentences say what the papers report.
glioma (4 papers, 2019 to 2025). A benign or malignant brain and spinal cord tumor that arises from glial cells (astrocytes, oligodendrocytes, ependymal cells). "Variants in 1q32.1 (MDM4), 16q12.1 (HEATR3), 22q13.1 (SLC16A8) and 11q14.1 were also associated with increased risk of IDH-wt glioma although the results were not significant after adjusting for multiple comparison." (PMID 31842352, 2019). "The expression levels of EMB, LDHA, SLC16A1, SLC16A3, SLC16A8, PARK7, and PFKFB2 were lower in 1p/19q Codel glioma than those in non-Codel glioma." (PMID 36698888, 2022).
age-related macular degeneration (2 papers, 2021 to 2022). Age-related loss of vision in the central portion of the retina (macula), secondary to retinal degeneration. "The study of Klipfel L demonstrates the loss of transport function of the hypomorphic allele in the SLC16A8 gene and offers a methodological framework for the investigation of other SLC16A8 alleles linked to age-related macular degeneration." (PMID 36160034, 2022).
clear cell renal cell carcinoma (1 paper, 2022). "We selected lactic acid metabolism and transporter related twenty-one genes for LASSO cox regression analysis in the E-MTAB-1980 cohort, and finally screened three genes (PNKD, SLC16A8, SLC5A8) to construct a clinical prognostic model for patients with clear cell renal cell carcinoma." (PMID 35456426, 2022).
geographic atrophy (1 paper, 2023). "Solute carrier (SLC) groups of membrane transport proteins are crucial for visual function, as the deletion of SLC16A8 in mice leads to vision loss and decreased expression of SLC16A8 in eyes with geographic atrophy (GA) increases disease severity." (PMID 37190063, 2023).
glioblastoma (1 paper, 2015). The most malignant astrocytic tumor (WHO grade IV). "In view of lactate accumulation upon PDHC inhibition, the ability of cancer cells to extrude lactate faster through higher expression of SLC16A8, aided by SLC16A3 in U87 cells, may also contribute to the higher resistance to the P-analogs of the glioblastoma vs HEK293 cell lines." (PMID 26503465, 2015). "Expression of highly-specific lactate transporters SLC16A8 (MCT3) and SLC16A3 (MCT4), which prefer lactate over pyruvate, is pronounced in glioblastoma cell lines T98G and U87, but not detectable in HEK293 cells." (PMID 26503465, 2015).
tumor (6 papers, 2021 to 2024). "Pan-cancer, SLC16A3 and SLC16A8 are somatically mutated in less than 1% of tumours." (PMID 37999800, 2024). "After detection, it was found that RIMS3 was significantly increased in normal samples, while SLC16A8 was substantially upregulated in tumor samples, which indicated that RIMS3 was a suppressor gene while SLC16A8 was an oncogene in CRC." (PMID 36160034, 2022). "LAGs like SLC16A8, SLC16A1, and LDHB have a higher methylation ratio in tumor tissue than in normal tissue; a lower methylation ratio of SLC16A7 and SLC16A3 is noticed in that comparison." (PMID 37122693, 2023). "Among most of these tumor types, a negative correlation between gene methylation and mRNA expression was revealed by calculating the Spearman correlation, including HIF1A, SLC16A1, UEVLD, SLC16A8, PFKFB2, LDHB, and SLC16A3." (PMID 37122693, 2023).
cancer (5 papers, 2015 to 2023). A tumor composed of atypical neoplastic, often pleomorphic cells that invade other tissues. "Compared to MCT1 and MCT4, MCT2/SLC16A7 and MCT3/SLC16A8 are less often expressed in cancers." (PMID 28107190, 2017). "A significant decrease in the transcriptional level was observed for SLC16A7 in the cancer tissues, while a non-significant decrease persisted in the case of SLC16A8." (PMID 37934721, 2023).
SLC16A8 also shares sentences with these, for which no sentence is quoted: ovarian carcinoma (1 paper).